HIC2 (HIC ZBTB transcriptional repressor 2)
Description:
Transcriptional repressor.
Synonyms: HRG22; KIAA1020; ZBTB30; ZNF907
Tractability: Antibody: its Gene Ontology location is reachable by antibodies, with high confidence.
Gene: Protein-coding gene on chromosome 22 (21,416,504 to 21,451,463, forward strand). Ensembl gene ENSG00000169635.
Subcellular location: Nucleus
Subcellular location (Human Protein Atlas): Nucleoplasm
Gene Ontology:
Molecular function: protein binding; DNA binding; DNA-binding transcription repressor activity, RNA polymerase II-specific; RNA polymerase II cis-regulatory region sequence-specific DNA binding
Biological process: negative regulation of DNA-templated transcription; negative regulation of transcription by RNA polymerase II; regulation of cytokine production; regulation of immune system process
Cellular component: nucleoplasm; nucleus
Genetic constraint (gnomAD): Loss-of-function variants: 2 observed, 30.96 expected, observed/expected ratio (o/e) 0.0646, 90% interval 0.025 to 0.2. The upper end of that interval is the gene's LOEUF score, 0.2, which puts it in group 1 of 6, group 1 being the genes least tolerant of losing a copy. Missense variants: 713 observed, 832.32 expected, observed/expected ratio (o/e) 0.86, 90% interval 0.81 to 0.91. Synonymous variants: 399 observed, 355.44 expected, observed/expected ratio (o/e) 1.12, 90% interval 1.03 to 1.22.
Homologues: Orthologues: chimpanzee HIC2 (99% identical), macaque HIC2 (98% identical), dog HIC2 (94% identical), guinea pig HIC2 (92% identical), rabbit HIC2 (92% identical), rat Hic2 (89% identical), mouse Hic2 (89% identical), pig HIC2 (86% identical), tropical clawed frog hic2 (61% identical), zebrafish hic2 (56% identical). Paralogues in human: HIC1 (45% identical), ZBTB7C (17% identical), ZBTB18 (16% identical), ZBTB16 (15% identical), ZBTB1 (14% identical), ZBTB42 (14% identical), PATZ1 (13% identical), PRDM1 (13% identical), ZBTB20 (13% identical), ZNF410 (13% identical), PRDM14 (13% identical), ZBTB45 (13% identical), and 24 more.
Diseases named in the same sentence as HIC2 in open-access papers:
HIC2 is named in the same sentence as 18 diseases in open-access papers, as found by Europe PMC text mining. Sharing a sentence is not in itself a finding about the gene and the disease. The quoted sentences say what the papers report.
glioblastoma (2 papers, 2023 to 2025). The most malignant astrocytic tumor (WHO grade IV). "Overexpression of HIC2 in glioblastoma cells (LN229 and U251) induced G2/M cell cycle arrest by down-regulating CDK1." (PMID 40650119, 2025). "We further investigated the growth inhibition role of HIC2 in an orthotopic glioblastoma‐bearing mice by using GL261 cell line in C57BL/6 mice." (PMID 36650953, 2023).
alopecia areata (1 paper, 2015). Loss of scalp and body hair involving microscopically inflammatory patchy areas. "Genes that were significant with at least two variables include: BTNL2 for alopecia areata, NOD2 for Crohn’s disease, PLA2R1 for membranous neuropathy, LMO1 for neuroblastoma, and TNPO3, UBE2L3, HLA-DRA, and HIC2 for systemic lupus erythematosus." (PMID 26170196, 2015).
bladder cancer (1 paper, 2016). "Our previous studies have shown that miR-193a-3p is involved in multi-drug resistance in both hepatocellular carcinoma and bladder cancer via the repression of different target genes, including SRSF2, PLAU, HIC2 and LOXL4." (PMID 27056900, 2016).
breast carcinoma (1 paper, 2022). "Our validation analysis confirmed that the gain of 5-hmC in TXNL1, BNIPL, CNIH3 and loss of 5-hmC in CHODL, ZBTB16, SP8, and HIC2 in breast cancer samples." (PMID 36230901, 2022).
glioma (1 paper, 2023). A benign or malignant brain and spinal cord tumor that arises from glial cells (astrocytes, oligodendrocytes, ependymal cells). "We further investigated the association between HIC2 DNA methylation and clinicopathologic features of glioma." (PMID 36650953, 2023). "With the increase in risk score, the survival rate of glioma patients significantly decreased, consistent with the results that HIC2 and IDH1 mutations were protective factors, while age and grade were risk factors in glioma." (PMID 36650953, 2023). "Furthermore, we found that 5 immune inhibitors (KDR, TIGIT, VTCN1, LAG3 and ADORA2A) and 2 immune stimulators (ICOS and TNFRSF25) were significantly associated with HIC2 in gliomas." (PMID 36650953, 2023). "In addition, DNA methylation levels of HIC2 were higher in IDH1 wild‐type glioma patients than in IDH1 mutation glioma patients (p < 0.0001)." (PMID 36650953, 2023). "Furthermore, low expression of HIC2 was closely associated with poor OS of glioma patients in TCGA database, in accordance with the data from GSE4412 and CGGA." (PMID 36650953, 2023). "As a 1p/19q codeletion, MGMT promoter methylation and IDH1 mutation is an important marker for the prognostic evaluation of glioma patients, and we investigated expression of HIC2 and this clinicopathologic feature." (PMID 36650953, 2023). "Meanwhile, enrichment analysis of HIC2 expression suggested that the mTOR signaling pathway was potential HIC2‐mediated pathways in glioma cells." (PMID 36650953, 2023). "We further performed BGS to detect the methylation of individual CpG sites on the HIC2 promoter of four glioma cell lines, and the results showed that HIC2 was highly methylated in four glioma cell lines." (PMID 36650953, 2023). "Because HIC2 was expressed at low levels in glioma samples, we further investigated the biological function of HIC2 in glioma based on HIC2 expression using GO and KEGG enrichment analyses." (PMID 36650953, 2023). "Multivariate Cox regression analysis suggested that HIC2 was an independent prognostic factor for gliomas." (PMID 36650953, 2023). "Collectively, these findings indicate that HIC2 is an independent prognostic factor in glioma patients and has high prognostic prediction ability." (PMID 36650953, 2023). "MSP assay result showed that expression of HIC2 in glioma cells was lower compared to normal immortalized astrocyte, while methylation level of HIC2 in glioma cells was reverse." (PMID 36650953, 2023). "We first assessed the DNA methylation status of the HIC2 promoter, since HIC2 is abnormally expressed in glioma samples." (PMID 36650953, 2023). "Collectively, our results demonstrated that HIC2 is highly methylated in glioma and that high DNA methylation levels of HIC2 at three CpG sites are associated with poor prognosis." (PMID 36650953, 2023). "When expression of HIC2 was upregulated, the proliferation of glioma cells was significantly inhibited both in vitro and in vivo." (PMID 36650953, 2023). "In summary, our study revealed that HIC2 is hypermethylated in glioma and that HIC2 is an independent protective factor in glioma, suggesting that HIC2 represents a novel biomarker for the prognosis prediction of gliomas." (PMID 36650953, 2023). "We found that HIC2 was expressed at lower levels in glioma cells than that in the immortalized astrocyte cells, consistent with the results that HIC2 is expressed at low levels in glioma samples." (PMID 36650953, 2023). "The promoter of HIC2 was highly methylated at three CpG sites, including cg13558199 (p < 0.05), cg20944928 (p < 0.05), and cg22869804 (p < 0.05), in glioma samples." (PMID 36650953, 2023). "Based on the expression levels of HIC2 in glioma cells, HIC2 was stably overexpressed in LN229, U251, and GL261 glioma cells." (PMID 36650953, 2023).
glioma (continued). "In this study, after a comprehensive bioinformatics and experimental analysis of the role of HIC2 in glioma, we found that HIC2 was epigenetically silenced by hypermethylation in its promoter and low expression of HIC2 indicated an unfavorable prognosis." (PMID 36650953, 2023). "The results showed that overexpression of HIC2 significantly impaired growth of GL261 glioma cells in vivo." (PMID 36650953, 2023). "Expression levels of HIC2 were significantly downregulated in glioma samples compared to control samples, as confirmed by TCGA and GTEx (p < 0.001), GEO (p < 0.001), and CGGA (p < 0.01) databases." (PMID 36650953, 2023). "Our findings suggest that HIC2 represents a tumor suppressor gene and prognostic biomarker for glioma progression and that overexpression of HIC2 inhibits the proliferation of glioma in vitro and in vivo by interacting with RNF44 and PTPRN2." (PMID 36650953, 2023). "In our study, GO and KEGG enrichment analysis implied an immune‐mediated role of HIC2 on glioma progression." (PMID 36650953, 2023). "To investigate expression levels of HIC2 in glioma samples, we first downloaded the expression profile of different grades of glioma from four databases: TCGA, GTEx, CGGA, and GEO." (PMID 36650953, 2023). "Because HIC2 is involved in immunomodulatory signaling pathways in gliomas, we further investigated the correlation between HIC2 expression and immune cell infiltration." (PMID 36650953, 2023). "The DNA methylation and mRNA expression profiles of HIC2 were downloaded from the Chinese Glioma Genome Atlas (CGGA), The cancer genome atlas (TCGA), The Genotype‐Tissue Expression (GTEx) and gene expression omnibus (GEO) databases." (PMID 36650953, 2023). "This study aimed to investigate the function of HIC2 and whether it could be a prognostic biomarker in glioma." (PMID 36650953, 2023). "Therefore, we further performed a Co‐IP assay by cotransfecting a plasmid containing RNF44 with a Flag tag or HIC2 with an HA tag into glioma cells to evaluate the interaction between HIC2 and RNF44." (PMID 36650953, 2023). "We found that HIC2 was hypermethylated and expressed at low levels in glioma samples." (PMID 36650953, 2023). "Next, expression levels of HIC2 and clinicopathologic features of glioma were analyzed." (PMID 36650953, 2023). "Furthermore, expression of HIC2 negatively correlated to the markers of M2‐type TAMs and N2 type TANs, implying an anti‐tumor function of HIC2 on glioma progression by mediating macrophage and neutrophil infiltration." (PMID 36650953, 2023). "However, further experimental data found that HIC2 acts as a tumor suppressor gene and transcription repressor in glioma cells." (PMID 36650953, 2023). "Moreover, to investigate the prognostic significance of DNA methylation of HIC2 in glioma patients, survival analysis was performed, and we found that high DNA methylation levels of HIC2 at three CpG sites predicted poor prognosis in glioma patients, implying a tumor suppressor role of HIC2." (PMID 36650953, 2023). "Taken together, HIC2 could be used as a potentially independent prognostic biomarker for gliomas." (PMID 36650953, 2023). "We were curious whether HIC2 plays the same role as HIC1 in glioma." (PMID 36650953, 2023). "Therefore, our findings confirmed the tumor suppressor role of HIC2 in glioma." (PMID 36650953, 2023). "The results of the proliferation assay showed that upregulating HIC2 impaired cell growth in both LN229 and U251 glioma cells." (PMID 36650953, 2023). "However, the actual role of HIC2 in glioma progression remains unclear." (PMID 36650953, 2023). "Overexpression of HIC2 decreased the phosphorylation levels of mTOR, AKT and 70S6k in LN229 and U251 glioma cells." (PMID 36650953, 2023). "To further investigate the function of HIC2 in glioma cells, we first assessed the expression of HIC2 in six glioma cell lines and one nontumor immortalized astrocyte cell line." (PMID 36650953, 2023).
glioma (continued). "Because glioma patients with low HIC2 expression have poor prognosis, we next performed univariate and multivariate Cox regression analyses using data from TCGA and CGGA to explore whether HIC2 is an independent prognostic factor in glioma patients." (PMID 36650953, 2023). "The relative luciferase activity in LN229 glioma cells was markedly decreased after cotransfection of HIC2 and WT‐PTPRN2‐luc or HIC2 and Mut‐E2‐luc, while luciferase activity was not affected after cotransfection of HIC2 and Mut‐E1‐luc." (PMID 36650953, 2023).
cancer (7 papers, 2015 to 2023). A tumor composed of atypical neoplastic, often pleomorphic cells that invade other tissues. "This target, hypermethylated in cancer 2 (hic2), encodes a BTB-zinc finger (BTB-ZF) transcription factor that contains multiple predicted let-7 and miR-125 sites in its 3’UTR." (PMID 27508495, 2016). "For example de novo motif analysis revealed enrichment of potential cooperative factors that exert known roles in cancer progression (e.g., HIC2, KLF3, SOX2); the relative impact of these likely contributing factors should be assessed." (PMID 34773073, 2022). "These included several cancer-associated genes such as MKL1, EP300, NF2, and HIC2 and chromatin binding genes BRD1, HIRA, and HDAC10." (PMID 25909290, 2015). "The DSV (g.4260 T > C) may create a binding site for zinc finger transcriptional repressor hypermethylated in cancer 2 (HIC2) and modify binding sites for TFAP2B and TFAP2C." (PMID 31775637, 2019). "HIC ZBTB transcriptional repressor 2 (HIC2) is also known as HRG22, ZBTB30, ZNF907 or hypermethylated in cancer." (PMID 36650953, 2023).
tumor (3 papers, 2015 to 2023). "The results showed that expression levels of HIC2 were gradually decreased with increasing tumor grade from normal to grade IV in the TCGA, GTEx, and CGGA databases." (PMID 36650953, 2023). "We found that HIC2 expression correlated with macrophage and neutrophil infiltration, which implied that HIC2 played a potential role in the tumor microenvironment." (PMID 36650953, 2023). "We then identified lists of genes specifically overexpressed in each human group by pair-wise Welch t-test; clustering mouse tumours on this set of genes also clearly delineated mIC from mE/IC and showed similarities between mIC and hIC2 patterns." (PMID 26818002, 2016). "In our previous study, we showed that miR-193a-3p promotes Pa chemoresistance in BCa cells in tumor xenografts of nude mice by repressing three of its targets in the tumor tissues: SRSF2, PLAU and HIC2." (PMID 25991669, 2015).
HIC2 also shares sentences with these, for which no sentence is quoted: Crohn disease (1 paper); DiGeorge syndrome (1); hepatocellular carcinoma (1); metabolic disease (1); mood disorder (1); neuroblastoma (1); primitive neuroectodermal tumor (1); psychosis (1); schizophrenia (1); systemic lupus erythematosus (1); thrombosis (1).